ASS1 (argininosuccinate synthase 1)
Diseases named in the same sentence as ASS1 in open-access papers (continued):
Sharing a sentence is not in itself a finding about the gene and the disease.
breast carcinoma (continued). "To determine the significance of ASS1 downregulation in breast cancer patients with respect to disease outcome, we used publicly available datasets." (PMID 40645971, 2025). "Further research into the role of estrogen in protecting ASS1 promoter methylation and therapeutic implications is expected to enhance treatment strategies of this understudied subtype of breast cancer." (PMID 40645971, 2025). "Mice with high ASS1 level display significantly lower objective response rates to anti-PD-1 therapy in xenograft model, and breast cancer patients with high ASS1 levels have more metastases and poor progression-free survival." (PMID 41460862, 2025). "This indicates that the low and high invasive breast cancer cell lines regulate their oncogenic potentials via ASS1 differently." (PMID 38283944, 2023). "For breast cancer, our data demonstrated that the expression of ASS1 in the tumor tissues of BRCA is lower than the corresponding normal tissues, and high ASS1 expression is associated with poor overall survival." (PMID 38053661, 2023). "The results of the CPTAC datasets showed higher expression of ASS1 total protein in the primary tissue of breast cancer, clear cell RCC, GBM, HNSC (Head and neck squamous cell carcinoma), LIHC, and UCEC (p<0.001) than in normal tissues." (PMID 38053661, 2023). "Expression of Arginase1 (Arg1) and Arginosuccinate lyase (Asl) was elevated by 4T1 breast cancer while the mRNA levels of Ornithine carbamoyltransferase (Otc) and Arginosuccinate synthase 1 (Ass1) were reduced." (PMID 35705545, 2022). "Of note, aspartate and uracil were simultaneously elevated in the livers of 4T1 breast cancer-bearing mice, accompanied by upregulation of Cad and by downregulation of Ass1 (respectively)." (PMID 35705545, 2022). "Correlation analysis between PGAM1, ASS1, and clinicopathologic features of the patients with breast cancer." (PMID 35674458, 2022). "In ASS1-high tumor cells, such as prostate cancer, breast cancer and renal cell carcinoma, the presence of arginase in the TME can cause adverse effects, especially regarding the immune response to cancer cells." (PMID 35265615, 2022). "The results showed that the average concentration of ASS1 in serum of patients with breast cancer was 2.868 ± 0.53 ng/mL, which was lower than that in the serum of healthy control population (3.133 ± 0.615 ng/mL, p = 0.0508)." (PMID 35941558, 2022). "For example, the ASS1-positive breast cancer cell line MCF-7 is resistant to ADI-PEG20 monotherapy, but the response to ADI-PEG20 coupled with radiation therapy is synergistic." (PMID 35113813, 2022). "Here, the authors show an alternative therapeutic approach where ASS1 activity is increased by the pesticide spinosyn A and is shown to inhibit breast cancer cell proliferation." (PMID 33859183, 2021). "To define the role of ASS1 in breast cancer, we examined the expression of ASS1 in a series of breast cancer cell lines, and found that MCF-7 cells have relative high while MDA-MB-231cells have relative low levels of ASS1 expression." (PMID 33859183, 2021). "Consistently, the inhibitory effect (IC50) of SPA and LM-2I on the proliferation of different breast cancer cell lines was significantly correlated with the endogenous expression levels of ASS1 in the cells." (PMID 33859183, 2021). "We further demonstrated that dietary limitation of arginine can be effective in retarding the growth of arginine auxotrophic (ASS1-low) breast cancer BT-549 cells." (PMID 30393775, 2018). "The present work provides insights into a mechanistic link between cell signaling pathways and metabolic pathways in arginine-starved, ASS1-low breast cancer cells." (PMID 30393775, 2018). "This formulation allows both extracellular and intracellular depletion arginine depletion and was reported to overcome ADI-resistance and induce cytotoxicity in ASS1-expressing breast cancer in vitro." (PMID 28750681, 2017).
breast carcinoma (continued). "However, analysis of 1980 breast cancer patients from the METABRIC dataset in our study revealed a significant correlation of high ASS1 with poor overall survival." (PMID 40645971, 2025). "This low ASS1 abundance is significantly correlated with lower survival rates in breast cancer." (PMID 39973065, 2025). "Meanwhile, the somatic silence or downregulation of ASS1 is very common in various cancers, and ASS1 might be a tumor suppressor in breast cancer." (PMID 40761790, 2025). "In addition, the IHC results showed that ASS1 was negatively associated with breast cancer recurrence, whereas PHGDH was positively associated with breast cancer recurrence, and ASS1 was negatively associated with PHGDH in TNBC patient tissue." (PMID 38710705, 2024). "Knockdown of phosphoglycerate mutase 1 (PGAM1) could reconstruct the expression of ASS1 in breast cancer (BC) cells, resulting in a decrease in tumor growth and exerting antitumor effects via cAMP/AMPK/CEBPB axis." (PMID 35674458, 2022). "As the key enzyme for arginine biosynthesis, we speculated that the expression of ASS1 in patients with breast cancer might also be different compared with that in normal people." (PMID 35941558, 2022). "Lower expression of ASS1 was also observed in breast cancer tissues than the adjacent tissues." (PMID 35941558, 2022). "SPA and LM-2I treatment results in significant enhancement of ASS1 enzymatic activity in breast cancer cells, particularly in those cancer cells with low ASS1 expression, leading to reduced pyrimidine synthesis and consequently the inhibition of cancer cell proliferation." (PMID 33859183, 2021). "Our study demonstrates that ASS1 knockdown increases while ASS1 overexpression decreases breast cancer cell proliferation and tumor development, and that down-regulation of ASS1 expression is significantly related to tumor relapse, indicating that ASS1 function as tumor suppressor in breast cancer." (PMID 33859183, 2021). "Altogether, these results support that ASS1 act as tumor suppressor in breast cancer." (PMID 33859183, 2021). "Moreover, our findings highlight that, in the absence of exogenous citrulline (i.e., in commercial media), ASS1-proficient breast cancer cells also produce argininosuccinate mainly via reversed ASL activity." (PMID 30613774, 2019). "Previously, we showed that low ASS1 abundance predicts poor breast cancer survival." (PMID 30393775, 2018). "Next, ASS1-deficient BT-549 and MDA-MB-435 breast cancer cells were used to investigate whether the metabolic alterations identified were a MDA-MB-231-specific phenomenon or a general characteristic of arginine auxotrophy." (PMID 30393775, 2018). "Cell death increase was also observed in other ASS1-null cancer cells within the panel tested, including the SCLC cell lines DMS 114 and H69 AR and the breast cancer cell line MDAMB231." (PMID 39898973, 2025). "In clinical samples of patients with breast cancer, LAP3 was confirmed to be upregulated, while ASS1 was downregulated compared with healthy control." (PMID 35941558, 2022). "It should be noted that in our survey of five prostate (PC3, CWR22Rv1, DU145) and breast cancer (MDA-MB-231 and BT-459) ADI-resistant cell lines, all restored ASS1 expression." (PMID 33664852, 2021). "Here, we show that ASS1 functions as a tumor suppressor in breast cancer, and the pesticide spinosyn A (SPA) and its derivative LM-2I suppress breast tumor cell proliferation and growth by binding to and activating ASS1." (PMID 33859183, 2021). "Arginine starvation has been shown to impair mitochondrial respiratory function in ASS1-deficient breast cancer cells, suggesting that arginine starvation therapy such as pegylated recombinant arginine deiminase (ADI-PEG20) could be an option for patients with low ASS1 expression." (PMID 31231467, 2019).
breast carcinoma (continued). "To test the effect of arginine starvation on tumor cells in vivo, we examined tumor growth in ASS1-low BT-549 and MDA-MB-231 breast cancer cell xenograft model subjected to dietary arginine restriction." (PMID 30393775, 2018). "Furthermore, ASS1 is associated with chemoresistance, invasion, recurrence, and poor clinical outcomes, including breast cancer, HCC, renal cell carcinoma, and prostate cancer, in which ASS1 expression is lost." (PMID 38710705, 2024). "Breast cancer cells lacking ASS1 undergo autophagy-dependent death when subjected to arginine starvation." (PMID 37445845, 2023). "Conversely, in ASS1-negative breast cancer cell lines, arginine deprivation reduces OXPHOS, which leads to mitochondrial dysfunction." (PMID 37804830, 2023). "This is consistent with previous studies demonstrating that not all breast cancer subtypes inactivate ASS1 expression to enhance their oncogenic property." (PMID 38283944, 2023). "ADI-PEG 20-based arginine starvation therapy has the potential to become a treatment option for breast cancer patients with low or absent levels of ASS1." (PMID 37445845, 2023). "The research of TNFAIP6, DHRS3, ASS1, RIPK4, VIM, and CD200 in breast cancer may indicate that those genes may play a crucial role in the development of breast cancer bone metastasis." (PMID 30918839, 2019). "More than 60% of breast cancer biosamples show low or absent ASS1 levels." (PMID 39973065, 2025). "Qiu6 found that ASS1 was either low or absent in more than 60% breast cancer bio-samples." (PMID 31000693, 2019). "Using the METABRIC dataset, we found that elevated ASS1 expression (upper quartile) is prognostic of poor overall survival (OS), when all subtypes were considered (p = 0.001), suggesting our findings are not generalizable to all breast cancer subtypes together." (PMID 40645971, 2025). "Based on these data, we hypothesize that ASS1 expression restores arginine metabolism in M231-ADIR cells, whereas TREM1 expression stimulates AKT/mTOR/STAT3 and a CCL2 feed-forward loop to provide survival signals contributing to ADI resistance in breast cancer cells." (PMID 33664852, 2021). "We also evaluated all endocrine-treated breast cancer patients in METABRIC, and ASS1 was not predictive of OS (data not shown)." (PMID 40645971, 2025). "Besides some published potential biomarkers of breast cancer bone metastasis were identified in our study, we also detected some novel biomarkers or their relationship with breast cancer bone metastasis has never been reported, such as TNFAIP6, DHRS3, ASS1, RIPK4, VIM, CD200." (PMID 30918839, 2019).
mesothelioma (27 papers, 2014 to 2025). A usually malignant and aggressive neoplasm of the mesothelium which is often associated with exposure to asbestos. "In particular, the pegylated arginine-degrading enzyme arginine deiminase (ADI-PEG20 or pegargiminase) has shown some survival benefits as a single agent in ASS1-deficient mesothelioma." (PMID 40918456, 2025). "Accordingly, arginine-depleting agents have been evaluated as therapeutic strategies in ASS1-deficient mesothelioma." (PMID 40918456, 2025). "The results provided by this clinical trial thus support the combination of arginine depletion and chemotherapy as a possible strategy for increasing survival outcomes in patients with ASS1-deficient mesothelioma." (PMID 40918456, 2025). "Collectively, our data indicate that ADI-PEG20-inducible cytokines orchestrate argininosuccinate fuelling of ASS1-deficient mesothelioma by macrophages." (PMID 37010783, 2023). "Observed in 63% of patients with mesothelioma, reduced or total loss of ASS1 protein expression results in the cancer cells becoming wholly dependent on extracellular arginine for survival." (PMID 36903394, 2023). "ADI-PEG20 also significantly improves progression-free survival in patients with ASS1-loss mesothelioma." (PMID 35910381, 2022). "In a study including 68 patients with ASS1 deficient mesothelioma, Szlosarek demonstrated a prolonged progression-free survival and a reciprocal increase in citrulline after treatment with pegylated arginine deiminase." (PMID 34444954, 2021). "Mesothelioma cells are often arginine auxotrophic owing to the loss of argininosuccinate synthetase 1 (ASS-1), a phenomenon that led to a phase II trial of the arginine-degrading agent PEGylated arginine deiminase (ADI-PEG20)." (PMID 34226685, 2021). "Similar to our results, ASS1 was also elevated in mesothelioma 3D spheroids and in human pleural mesotheliomas, although mesothelioma is considered by many to be an ASS1-deficient tumor." (PMID 33838671, 2021). "More importantly, ASS1-deficient mesothelioma cells were shown to autonomously demethylate their ASS1 promoter to gain resistance." (PMID 35582579, 2019). "In a phase II randomized clinical trial of ADI-PEG20 on mesothelioma patients, ADI-PEG20 improved PFS in patients with ASS1-deficient mesothelioma and the adverse effects observed in patients were tolerable." (PMID 28750681, 2017). "In the study, ADI-PEG20 treated ASS1-deficient mesothelioma cells showed decreased polyamine metabolite and enhanced polyamine synthetics enzymes in vitro." (PMID 28750681, 2017). "Although mesothelioma is considered by many to be an ASS1-deficient tumor, our results show that ASS1 is elevated at the mRNA and protein levels in mesothelioma 3D spheroids and in human pleural mesotheliomas." (PMID 26982031, 2016). "In fact, many publications describe mesothelioma as an ASS1-deficient tumor, and thus one that can be targeted with arginine deiminase (ADI), an enzyme that degrades arginine." (PMID 26982031, 2016). "Initially, this result was surprising, because mesothelioma is described in the literature as an ASS1-deficient tumor, whose auxotrophy for arginine can be targeted therapeutically." (PMID 26982031, 2016). "A study on ADI clinical trials has demonstrated that ADI can prolong progression-free survival in patients with ASS1-deficient mesothelioma (3.2 vs. 2.0 months), and that the overall patient survival in the ADI and control group is 15.7 and 12.3 months, respectively." (PMID 33791071, 2021). "Loss of ASS1 renders mesothelioma cells addicted to exogenous arginine, and this defect may be therapeutically exploited by pegylated arginine deiminase (ADI–PEG20), which works by clearing circulating arginine." (PMID 32226777, 2020). "In another recent study on mesothelioma, a weak point of ASS1-deficiency was reported." (PMID 28750681, 2017).
mesothelioma (continued). "Furthermore, when ASS1- deficient mesothelioma cells were treated with ADI-PEG20 and ODC inhibitor DFMO together, synthetic lethality was observed in vitro." (PMID 28750681, 2017). "Thus, there appear to be two groups of mesothelioma, those with ASS1 deficiency and those with upregulation of ASS1." (PMID 26982031, 2016). "Interestingly, ASS1 is thought to be deficient in mesothelioma." (PMID 26982031, 2016). "A novel strategy based on arginine deprivation selectively kills mesothelioma cells that lack argininosuccinate synthetase 1 (ASS1), the rate-limiting enzyme in arginine biosynthesis." (PMID 39758821, 2025). "generated a model of ADI-PEG20 resistance through the re-expression of ASS1 via demethylation of the ASS1 promoter in mesothelioma cells." (PMID 38053661, 2023). "In the Arginine Deaminase and Mesothelioma (ADAM) phase II trial, sixty-eight ASS1-deficient (as determined by IHC) MPM patients were enrolled and randomized 2:1 to receive ADI-PEG20 or best supportive care (BSC) as first or second line treatment." (PMID 37298116, 2023). "Taken together, our results support a role for ASS1-expressing TAMs under cytokine control mediating resistance to arginine deprivation via argininosuccinate as a critical metabolite fuelling mesothelioma growth." (PMID 37010783, 2023). "We studied the metabolic consequences of ASS1 epigenetic silencing in mesothelioma and bladder cancer cell lines, identifying reduced thymidine levels and increased levels of thymine and glutamine upon ADI-PEG20 treatment." (PMID 36903394, 2023). "The somatic silence of ASS1 expression is commonly observed in a wide range of tumors, such as mesothelioma, non-small-cell lung cancer, myxofibrosarcomas." (PMID 35910381, 2022). "For tumors (e.g., lymphomas, bladder, mesothelioma, prostate cancer) where ASS1 was silenced by methylation, demethylation of ASS1 promoter is the solution, although what triggers demethylation is not clear." (PMID 34298755, 2021). "Compared with 2D-cultured cells, 3D-cultured hepatocytes have demonstrated enzyme expression closer to mature hepatocytes, while 3D-cultured mesothelioma spheroids have shown upregulation in argininosuccinate synthase 1 (ASS1) expression." (PMID 31340547, 2019). "To investigate the levels of ASS1 protein expression in human mesothelioma tumors, we performed immunohistochemistry on 2 sets of tissue microarrays (TMA) containing samples from 176 pleural mesotheliomas." (PMID 26982031, 2016). "In the present work, we demonstrate for the first time that ASS1 is upregulated in mesothelioma 3D spheroids, is expressed in mesothelioma tumor samples, and exhibits a survival role." (PMID 26982031, 2016). "In another set of clinical samples, which contained 88 tumors along with their matching normal control tissue, ASS1 was significantly upregulated in mesothelioma samples compared to their matched normal controls." (PMID 26982031, 2016). "By comparing these datasets, we found 3 genes that were elevated in 3D compared to 2D as well as in mesothelioma compared to normal tissue: argininosuccinate synthetase 1 (ASS1), annexin A4 (ANXA4) and the major vault protein (MVP)." (PMID 26982031, 2016). "Other studies have also identified the presence of ASS1 in mesothelioma; in one review of transcriptome studies, ASS1 gene was one of the most prominently increased genes in mesothelioma." (PMID 26982031, 2016). "Further studies are underway to identify small molecules or other strategies to inhibit ASS1 both to understand its function in mesothelioma and to provide possible therapeutic options to patients with high ASS1 expression." (PMID 26982031, 2016).